ACTC1 (actin alpha cardiac muscle 1)
Diseases named in the same sentence as ACTC1 in open-access papers (continued):
Sharing a sentence is not in itself a finding about the gene and the disease.
prostate carcinoma (5 papers, 2020 to 2025). A carcinoma that arises from epithelial cells of the prostate gland. "At the top of the list for the proteins upregulated in advanced GC are α-actin cardiac muscle 1 (ACTC1), which is noted in prostate cancer, and complement C4." (PMID 35566209, 2022). "Through the application of bioinformatics technology, we identified the potential key genes associated with the occurrence and development of prostate cancer as FGF2, FLNA, VCL, FLNC, CAV1, ACTC1, and MYLK." (PMID 32547947, 2020). "High-expression ACTC1 (upregulated) in the gene expression profiling (GEP) profiling of prostate cancer using microarrays." (PMID 32986378, 2020).
bladder cancer (4 papers, 2011 to 2023). "Moreover, ACTC1 was reported to be a novel marker for prognosis of bladder cancer." (PMID 36406127, 2022). "Consistent with our study, previous studies have reported these key genes (TAGLN, CNN1, ACTC1, LMOD1) play important roles in bladder cancer." (PMID 38144520, 2023).
idiopathic dilated cardiomyopathy (3 papers, 2021 to 2025). Decreased function of the heart associated with cardiac enlargement and congestive heart failure, of unknown cause. "The observed decrease in Myl2 and Actc1 transcript levels suggests that these treatments may contribute to cellular dysfunctions typically associated with idiopathic dilated cardiomyopathy (IDC)." (PMID 39940670, 2025).
myopia (3 papers, 2011 to 2024). "Three genes for myopia, in 15p14 (GJD2, ACTC1) and 15q25 (RASGRF1), were identified to be susceptible loci in European Caucasians." (PMID 23649821, 2013). "Because the retina is a neural tissue, the expression of numerous genes linked to cardiac muscle (MYBPC3, ACTC1, MYL3, MYH7, MYH7B) or to skeletal muscle (MYL1, SMYD1, TNNI2, MYH1B, ACTA1, TNNT3) presents a conundrum for explaining a mechanism for myopia progression." (PMID 39028695, 2024).
nemaline myopathy (3 papers, 2014 to 2024). Nemaline myopathy (NM) encompasses a large spectrum of myopathies characterized by hypotonia, weakness and depressed or absent deep tendon reflexes, with pathologic evidence of nemaline bodies (rods) on muscle biopsy. "This is noteworthy because previous studies in mice have shown that increased expression of Actc1 can modify the phenotype of a different model of nemaline myopathy (ACTA1-related NM)." (PMID 38493359, 2024).
diabetic cardiomyopathy (2 papers, 2023 to 2024). Diabetic cardiomyopathy is a disorder of the heart muscle in people with diabetes. "Cluster 4 was enriched in genes of the ‘heart contraction’ (e.g., ACTC1, MYL3 and ACTA1) and ‘diabetic cardiomyopathy’ (e.g., TNNI3, MYH7 and GAS6)." (PMID 37766635, 2024).
Epithelial Ovarian Cancer (2 papers, 2012 to 2021). "Our spheroid cells also gained expression of human ACTC1 (αSMA) and VIM (Vimentin) mesenchymal markers, similar to ovarian cancer cell-formed spheroids, and doxorubicin-selected MCF-7/ADR cells indicating that an EMT had occurred during cancer progression of the CICs." (PMID 22284662, 2012).
familial dilated cardiomyopathy (2 papers, 2022 to 2025). A a genetic form of heart disease that occurs when heart (cardiac) muscle becomes thin and weakened in at least one chamber of the heart, causing the open area of the chamber to become enlarged (dilated). "Similarly, mutations in ACTC1 (alpha cardiac muscle actin) are implicated in familial dilated cardiomyopathy (DCM) and contribute to fibrosis in affected individuals." (PMID 40291288, 2025).
left ventricular noncompaction (2 papers, 2023). Left ventricular noncompaction (LVNC) is a rare cardiomyopathy characterized anatomically by prominent left ventricular trabeculae and deep intratrabecular recesses causing progressive systolic and diastolic dysfunction, conduction abnormalities, and occasionally thromboembolic events. "ACTC1 mutation was also detected in patients with left ventricular noncompaction (LVNC), repeated syncope, and resuscitated ventricular arrhythmias." (PMID 37108147, 2023).
lung carcinoma (2 papers, 2016 to 2022). "Detailed analysis of the ACTC1 region showed that three CpGs (cg10580056, cg03844894 and cg05432213) adjacent to cg17242351 were hypermethylated in lung cancer versus normal tissue and in addition, ACTC1 expression was reduced in lung tumor tissue from TCGA." (PMID 36142605, 2022). "The only paper that has evaluated Actc1 in lung cancer and this study showed that Actc1 expression was elevated in the human lung cancer cell line NCI-460 following treatment with paclitaxel." (PMID 26654940, 2016). "RNA sequencing revealed a number of genes differentially expressed in lung tumors lacking Akt2 and five of these genes, Actc1, Bpifa1, Mmp2, Ntrk2, and Scgb3a2 have been implicated in human lung cancer." (PMID 26654940, 2016).
ameloblastoma (1 paper, 2022). The most common odontogenic tumor, arising from the epithelial component of the embryonic tooth and usually affecting the molar-ramus region of the mandible or maxilla. "With these bioinformatic analyses it is possible that pathogenic ameloblastoma development involve these genes in intracellular regulation (AKT1, ACTC1, ADAM10, and APOA2) or for tumor microenvironment regulation (CRP, BCHE, APP, AGT)." (PMID 36553196, 2022).
Arthritis (1 paper, 2024). Inflammation of a joint. "The genes with the most significantly increased expression in the synovial tissues of the arthritis-protected Mg2800 diet group included Actc1 (actin alpha cardiac muscle 1) and Nr4a3 (nuclear receptor subfamily 4 group A member 3)." (PMID 39683640, 2024). "The genes with the most significantly increased expression in the synovial tissues of the arthritis-protected Mg2800 diet group included Snora34, Gnrh1, Actc1, Nr4a3, and Slc9a4." (PMID 39683640, 2024).
atrial fibrillation (1 paper, 2021). A disorder characterized by an electrocardiographic finding of a supraventricular arrhythmia characterized by the replacement of consistent P waves by rapid oscillations or fibrillatory waves that vary in size, shape and timing and are accompanied by an irregular ventricular response. "Novel variants in DCTN1, MYH14, and RBM20 were identified in Family 1 with cardiac and limb-girdle muscle involvement and in TRIM63, ACTC1, and TTN in the proband of family 2 with a distal lower limb phenotype and atrial fibrillation." (PMID 33170376, 2021).
congenital myopathies (1 paper, 2018). "Some reports have demonstrated that ACTC1 over-expression in postnatal skeletal muscle could effectively rescue ACTA1-related diseases, congenital myopathies caused by mutations in ACTA1." (PMID 29324704, 2018).
congestive heart failure (1 paper, 2021). Failure of the heart to pump a sufficient amount of blood to meet the needs of the body tissues, resulting in tissue congestion and edema. "The amount of troponin I, ACTC1, MHCβ transcripts did not change in the present study during cold stress and PHS in the broilers with hypertrophic heart or congestive heart failure whereas in the mammals, the regulation of these genes was strongly influenced." (PMID 34225204, 2021).
E. coli infection (1 paper, 2017). "In contrast, E. coli infection modulated only the expression of ACTC1 (actin, alpha, cardiac muscle 1) from among all of the cytoskeleton related factors." (PMID 28684793, 2017).
endotoxemia (1 paper, 2022). "Elevated serum ACTC1 has been associated with endotoxemia, potentially due to sarcomere disruption." (PMID 35682894, 2022).
hereditary cardiomyopathies (1 paper, 2024). "CAPN1 had heart enhanced interactions with ACTC1 and ACTN2, which participate in the formation of the actin cytoskeleton and are previously associated with hereditary cardiomyopathies." (PMID 38848015, 2024).
leiomyoma (1 paper, 2016). A well-circumscribed benign smooth muscle neoplasm characterized by the presence of spindle cells with cigar-shaped nuclei, interlacing fascicles, and a whorled pattern. "An increase in viscoelastic forces is associated with alteration of cell structure and actin organization, which lead to increased expression of several types of actins, including ACTC1, inducing leiomyoma growth." (PMID 27070597, 2016).
lymph node metastasis (1 paper, 2021). "In addition, GRK5/ACTC1 co-expression was associated with the following factors: histology, FIGO stage, lymph node metastasis, intraperitoneal metastasis, intestinal metastasis, vital status, differentiation grade, and ascites with tumor cells." (PMID 35223984, 2021). "There were significant relationships between ACTC1 expression and the clinicopathological parameters of EOC, such as the following factors: FIGO stage, lymph node metastasis, intraperitoneal metastasis, intestinal metastasis, vital status, and so on." (PMID 35223984, 2021).
malignant glioma (1 paper, 2023). A grade III or grade IV glioma arising from the central nervous system. "We previously reported that ACTC1 knockdown (KD) in a human malignant glioma cell line inhibited cell migration ability." (PMID 37891844, 2023). "One of these isoforms, high expression of actin alpha, cardiac muscle 1 (ACTC1), is a significant poor prognostic factor in malignant gliomas." (PMID 37891844, 2023). "Thus, we hypothesize that actin isoforms other than ACTC1 also involve cell migration and recurrence in malignant gliomas." (PMID 37891844, 2023). "It has been reported that ACTC1 is not involved in cell proliferation in malignant glioma." (PMID 37891844, 2023).
Mitochondrial myopathy (1 paper, 2021). "Indeed, one term (GO:0033275) included three DEGs (ACTC1, MYL4, and TNNT2) with essential roles in muscle function, the former of which has also been shown to be overexpressed in mitochondrial myopathy due to mitochondrial respiratory chain deficiency." (PMID 34488775, 2021).
recessive nemaline myopathy (1 paper, 2018). "However, upregulation of actc1a is sufficient to compensate for the loss of Actc1b mimicking the upregulation of ACTC1 in patients suffering from recessive nemaline myopathy caused by mutations in ACTA1." (PMID 29420541, 2018).
schizophrenia (1 paper, 2022). A major psychotic disorder characterized by abnormalities in the perception or expression of reality. "Furthermore, ACTC1 upregulation could be induced by over-expression of dysbindin, a protein found to be reduced in hippocampus in patients with schizophrenia." (PMID 35509884, 2022).
Sepsis (1 paper, 2016). Sepsis is defined as life-threatening organ dysfunction caused by a dysregulated host response to infection. "Choline treatment attenuated overexpression of contractile protein actin alpha cardiac muscle-1 (ACTC1) at 48 h after LPS, indicating a protective effect of choline treatment on sepsis-induced myocardial dysfunction (SIMD)." (PMID 27646125, 2016).
Sinus bradycardia (1 paper, 2024). Bradycardia related to a mean resting sinus rate of less than 50 beats per minute. "Still, some gene mutations, such as NOTCH genes, ACTC1, MYH7, MYBPC3, TTN, and HCN4, among others, have been implicated with the HCN4 gene responsible for sinus bradycardia in some patients." (PMID 39677872, 2024).
ventricular tachycardia (1 paper, 2025). A disorder characterized by an electrocardiographic finding of three or more consecutive complexes of ventricular origin with a rate greater than a certain threshold (100 or 120 beats per minute are commonly used). "An ACTC1 variant was identified in the proband and his father, both of whom presented with ventricular tachycardia." (PMID 41287789, 2025). "The proband inherited both the CACNA1C and ACTC1 variants from his father (III-2), who has HCM and non-sustained ventricular tachycardia." (PMID 41287789, 2025).
cancer (10 papers, 2012 to 2025). A tumor composed of atypical neoplastic, often pleomorphic cells that invade other tissues. "Mesenchymal migration, induced by lamellipodia formation, is a type of cancer cell migration, and we verified that either ACTC1 or ACTA2 KD significantly reduced lamellipodia formation." (PMID 37891844, 2023). "There are evidences that indicate the potential role of ACTC1 overexpression in cell motility and cancer cell survival." (PMID 36500393, 2022). "There was a significant difference on the GRK5, ACTC1, and GRK5/ACTC1 expression between the cancer and paratumor tissues (p < 0.0001, p < 0.0001, p < 0.0001)." (PMID 35223984, 2021). "Previous studies showed that ASPM, ACTC1, and CCNB1 are related to cancer prognosis." (PMID 34434217, 2021). "Furthermore, a targeted drug for ACTC1, DEXAMETHASONE, is commonly used in cancer treatment to alleviate side effects induced by cancer therapy, control cancer-related inflammation and immune responses as part of cancer treatment." (PMID 39968416, 2025).
tumor (8 papers, 2021 to 2025). "Analysis of samples in TCGA demonstrated that ACTC1 expression was higher in tumor samples, correlating with the result that patients with high ACTC1 expression had poor prognoses." (PMID 38358910, 2024). "The expression of GRK5 or ACTC1 in all of the matched paratumor tissues was set as 1.00 ± 0.00, and the expression in each of the tumor tissues was compared with that in the matched paratumor tissues." (PMID 35223984, 2021). "Immune infiltration analysis revealed that the expression levels of TNNI3, TNNT1, ACTC1, and MYH11 were correlated with the level of immune cell infiltration and tumor purity." (PMID 36514150, 2022). "Furthermore, we found that TNNT1, ACTC1, and MYH11 expression levels were negatively correlated with tumor purity, while TNNI3 expression levels were positively correlated with tumor purity." (PMID 36514150, 2022). "Interestingly, this cluster also has an elevated expression of MYH3, an embryonic form of myosin heavy chain, several cardiac cytoskeletal genes (ACTC1, TNNT2), and SERPINB9, which has previously been shown to protect tumor cells from granzyme B secreted by cytotoxic T lymphocytes." (PMID 41373578, 2025).
heart diseases (6 papers, 2012 to 2024). "ACTC1 encodes actin, which is involved in various types of cell motility, especially cardiac diseases." (PMID 36277688, 2022). "Both Myl3 and Actc1 were included by KEGG in the circulatory pathways ASC and CMC, and also in HCM and DIL cardiac disease pathways." (PMID 38534766, 2024). "A lack of ACTC1 may induce apoptosis, which plays a crucial role in embryological development and may also lead to disruption of organ differentiation, specifically defects associated with heart diseases." (PMID 33923632, 2021).
myopathy (4 papers, 2014 to 2025). A disease of the muscle in which the muscle fibers do not function properly. "Alternatively, one could speculate that the constipation and mild ventricular dysfunction seen in NAA80 individuals reflect a minor ACTG2 and ACTC1 dysfunction, in a similar way as the mild myopathy of NAA80 individuals reflects a minor form of the severe, lethal myopathy seen in ACTA1 individuals." (PMID 34805998, 2021).
cardiovascular disease (2 papers, 2023). "Notably, the ACTC1 gene is also associated with other forms of cardiovascular disease." (PMID 37195695, 2023).
adenocarcinoma (1 paper, 2018). A common cancer characterized by the presence of malignant glandular cells. "In the LIMMA analysis of any virus-infected (Virus(+)) (n = 8) versus uninfected primary adenocarcinoma specimens (Virus(−)) (n = 2), ACTC1 and PCSK2 were found to be significantly down-regulated in Virus(+)." (PMID 30134863, 2018).
metabolic disease (1 paper, 2017). A congenital disorder (due to inherited enzyme abnormality) or acquired (due to failure of a metabolically important organ) disorder resulting from an abnormal metabolic process. "Most of these P/LP variants were found in validated minor sarcomere genes (ACTC1, MYL2 and MYL3) and genes related to metabolic diseases (GLA and PRKAG2)." (PMID 28771489, 2017).
mitochondrial disease (1 paper, 2023). "Defects in sarcomere genes, such as MYH7, MYBPC3, TNNT2, TPM1, ACTC1, and TTN have been reported as causative for LVNC and LVNC is also commonly associated with mitochondrial diseases." (PMID 37186429, 2023).
ACTC1 also shares sentences with these, for which no sentence is quoted: familial hypertrophic cardiomyopathy (3 papers); myocardial infarction (3); arrhythmogenic right ventricular cardiomyopathy (2); infection (2); actin accumulation myopathy (1); aniridia (1); arthrogryposis (1); asymmetrical septal hypertrophy (1); atherosclerosis (1); Danon disease (1); familial atrial fibrillation (1); familial hypercholesterolemia (1); fracture (1); glycogen storage diseases (1); head and neck cancer (1); Hepatic fibrosis (1); iris hypoplasia (1); ischemia reperfusion injury (1); laminopathies (1); long QT syndrome (1); lung adenocarcinoma (1); lung squamous cell carcinoma (1); Marfan syndrome (1); myxoma (1); non-small cell lung carcinoma (1); Obesity (1); ocular coloboma (1); ovarian cancer (1); polyp (1); psychiatric disorder (1).
A further 7 diseases each share a sentence with ACTC1 in 1 paper.